MOGAT3 (monoacylglycerol O-acyltransferase 3)
Description:
Catalyzes the formation of diacylglycerol from 2-monoacylglycerol and fatty acyl-CoA. Also able to catalyze the terminal step in triacylglycerol synthesis by using diacylglycerol and fatty acyl-CoA as substrates. Has a preference toward palmitoyl-CoA and oleoyl-CoA. May be involved in absorption of dietary fat in the small intestine by catalyzing the resynthesis of triacylglycerol in enterocytes. Also able to use 1-monoalkylglycerol (1-MAkG) as an acyl acceptor for the synthesis of monoalkyl-monoacylglycerol (MAMAG).
Synonyms: MGAT3; DC7; DGAT2L2
Tractability: Antibody: UniProt predicts a signal peptide or a membrane-spanning region. PROTAC: UniProt records ubiquitination sites on it.
Target class: Enzyme; Transferase
Chemical probes: PF-06471553 (high quality)
Gene: Protein-coding gene on chromosome 7 (101,195,007 to 101,201,080, reverse strand). Ensembl gene ENSG00000106384.
Subcellular location: Endoplasmic reticulum membrane; Cytoplasm, perinuclear region
Pathways (Reactome):
Metabolism: Triglyceride biosynthesis
Gene Ontology:
Molecular function: 2-acylglycerol O-acyltransferase activity; diacylglycerol O-acyltransferase activity; acyltransferase activity, transferring groups other than amino-acyl groups; retinol O-fatty-acyltransferase activity
Biological process: monoacylglycerol biosynthetic process; triglyceride biosynthetic process; retinol metabolic process
Cellular component: endoplasmic reticulum membrane; perinuclear endoplasmic reticulum membrane; perinuclear region of cytoplasm
Genetic constraint (gnomAD): Loss-of-function variants: 39 observed, 36 expected, observed/expected ratio (o/e) 1.08, 90% interval 0.84 to 1.41. The upper end of that interval is the gene's LOEUF score, 1.41, which puts it in group 5 of 6, group 1 being the genes least tolerant of losing a copy. Missense variants: 439 observed, 451.03 expected, observed/expected ratio (o/e) 0.97, 90% interval 0.9 to 1.05. Synonymous variants: 209 observed, 185.46 expected, observed/expected ratio (o/e) 1.13, 90% interval 1.01 to 1.26.
Homologues: Orthologues: chimpanzee MOGAT3 (99% identical), macaque MOGAT3 (96% identical), dog MOGAT3 (71% identical), tropical clawed frog mogat3 (52% identical), zebrafish mogat3b (50% identical), Caenorhabditis elegans Y53G8B.2 (39% identical), Caenorhabditis elegans K07B1.4 (39% identical), Drosophila melanogaster Dgat2 (38% identical), Caenorhabditis elegans dgat-2 (38% identical), Drosophila melanogaster CG1941 (37% identical), Drosophila melanogaster CG1946 (37% identical), Caenorhabditis elegans dgtr-1 (37% identical). Paralogues in human: DGAT2 (50% identical), MOGAT2 (45% identical), DGAT2L6 (44% identical), AWAT1 (43% identical), MOGAT1 (42% identical), AWAT2 (39% identical).
Diseases named in the same sentence as MOGAT3 in open-access papers:
MOGAT3 is named in the same sentence as 4 diseases in open-access papers, as found by Europe PMC text mining. Sharing a sentence is not in itself a finding about the gene and the disease. The quoted sentences say what the papers report.
lipid metabolic disorders (1 paper, 2018). "Although results indicate that the metabolic mechanism of lipid regulation by MGAT1 and MOGAT3 was altered, evidence of association between lipid metabolic disorders caused by aberrant expression of MGAT1/MOGAT3 and PCa are lacking." (PMID 29692867, 2018).
tumor (1 paper, 2024). "Similarly, MOGAT3 is believed to maintain glyceride homeostasis in the human intestine and liver; however, the functions of MOGAT3 in physiological processes and tumor progression remain to be clarified." (PMID 39436710, 2024). "Hypoxia-induced resistance upregulates MOGAT3, enhancing DAG accumulation and tumor resilience." (PMID 39436710, 2024). "Monotherapy with Pf reduced the intratumoral DAG, but did not affect resistant PDX tumor growth, suggesting that MOGAT3-regulated levels of intratumoral DAG determine the treatment response to dual therapy." (PMID 39436710, 2024). "Next, we observed MOGAT3, but not MOGAT1 or MOGAT2, markedly elevated in resistant PDX tumors and RKO EC-R cells compared with respective sensitive tumor cells." (PMID 39436710, 2024).
MOGAT3 also shares sentences with these, for which no sentence is quoted: hair diseases (1 paper); metastatic colorectal cancer (1).